PFKFB3 (6-phosphofructo-2-kinase/fructose-2,6-biphosphatase 3)
Diseases named in the same sentence as PFKFB3 in open-access papers (continued):
Sharing a sentence is not in itself a finding about the gene and the disease.
cancer (continued). "In addition to promoting glycolytic function in cancer cells, PFKFB3 was found to be involved in regulating several cellular events, like cell cycle pathway, DNA damage/repair, autophagy, macropinocytosis, and metastasis." (PMID 35804016, 2022). "Analysis of the whole kinome (779 kinases) siRNA screen, showed an overexpression of 6-phosphofructo-2-kinase fructose-2,6-biphosphatase 3 (PFKFB3), a positive regulator of glycolysis in adipocytes and cancer cells, as a positive regulator of insulin/IGF-1 pathway." (PMID 34208601, 2021). "PFKFB3 is one of the pivotal glycolytic enzymes which promotes cancer cell proliferation." (PMID 34079757, 2021). "Moreover, the proapoptotic effect of suppressed PFKFB3 activity can be explained by increased expression of cyclin-dependent kinase inhibitor 1B (p27) in cancer cells following PFKFB3 inhibition." (PMID 33922320, 2021). "On the other hand, PFKFB3 (which is expressed in cancer cells) has a 700 fold higher kinase activity, which means that glycolytic flux is essentially maximally activated and thus contributes to the Warburg effect in cancer cells." (PMID 34282152, 2021). "In this study, Pfkfb3 (6-phosphofructo-2-kinase/fructose 2,6-biphosphatase 3) was identified as a gene that was highly expressed in metastatic cells but downregulated in dormant cancer cells." (PMID 33816262, 2021). "Interestingly, all the used cancer cells presented intrinsic differences in their response to a PFKFB3 blockade upon KAN0438757 treatment." (PMID 33671096, 2021). "Thus targeting PFKFB3 opens up therapeutic possibilities to improve the efficacy of ICL-inducing cancer treatments." (PMID 34298817, 2021). "Specifically, SRC-2 is required for progesterone-induction of 6-phosphofructo-2-kinase/fructose-2, 6-bisphosphatase 3 (PFKFB3), a bifunctional enzyme that is indispensable for a myriad of cellular processes from embryogenesis, post-natal cellular proliferation to cancer progression." (PMID 33898429, 2021). "PFKFB3 has been recognized as an important metabolic target in cancer." (PMID 33420377, 2021). "PFKFB3 is also important in the metastatic cascade since its expression in endothelial cells, which are hyperglycolytic, promotes angiogenesis and the formation of cancer typical leaky vessels, favoring the intravasation and metastatic spread of cancer cells." (PMID 34150624, 2021). "So, the role of autophagy in the degradation of Pfkfb3 protein was studied in dormant cancer cells." (PMID 33816262, 2021). "In light of this evidence, it is clear that targeting PFKFB3 could have important clinical benefits for cancer therapy." (PMID 33407885, 2021). "Additionally, related research shows that cancer cells with PFKFB3 modificated post‐translationally, such as phosphorylation, acetylation, and methylation, can better accommodate to glucose metabolism in different stress conditions." (PMID 33931981, 2021). "We previously reported that PFKFB3 relocates to DSBs upon ionizing radiation (IR), allowing for the assembly of key HR repair proteins into foci, required for functional DNA repair and cancer cell survival upon IR." (PMID 34298817, 2021). "Hence, previous publications have shown that inhibitors targeting PFKFB3 have been found to suppress aerobic glycolysis, decrease glucose uptake, and induce cancer cell autophagy." (PMID 35008356, 2021). "PFKFB3 is frequently overexpressed in diverse cancers and stimulated by oncogenic signaling." (PMID 34079757, 2021). "Combining anti-CTLA4 agents, such as ipilimumab, and PFKFB3 might simultaneously reinforce the immune reaction to cancer and attenuate cancer cell metabolism." (PMID 33671514, 2021). "PFKFB3 is an enzyme that regulates glycolysis and is upregulated in several cancers." (PMID 33302475, 2020). "Previous studies concerning PFKFB3 mainly focused on its role in cancer." (PMID 31880389, 2020).
cancer (continued). "In our study, we found that, after TOX knockdown, some proliferation and apoptosis-associated genes, such as PFKFB3, CDK5 and CKKN2A, were up- or down-regulated and most DEGs were enriched in cellular process and cancer pathways, which highlights the importance of TOX in cancer process." (PMID 31676945, 2020). "An increased PFKFB3 expression promotes proliferation and carcinogenesis, and its inhibition could be crucial for treating inflammations and cancer." (PMID 32717953, 2020). "PFKFB3 enhances glycolysis to promote cancer cell proliferation." (PMID 32198345, 2020). "Taken together, these data show that by inhibiting PFKFB3 K302 ubiquitination, AGPG enhanced PFKFB3 stability and therefore led to the increased accumulation of PFKFB3 in cancer cells, thereby increasing F-2,6-BP synthesis and subsequently promoting cell cycle progression by regulating p27 and CDK1." (PMID 32198345, 2020). "Our analysis clearly indicates that expression of PFKFB3/4 isoenzymes may have a key prognostic value for several cancers." (PMID 31754349, 2019). "Besides displaying the highest ratio of kinase/phosphatase, PFKFB3 is highly expressed in a variety of cancer cells, and can be induced by hypoxia and inflammatory stimuli." (PMID 31671668, 2019). "Therefore, it is possible to utilize PFKFB3 as a target for cancer therapy and overcome chemotherapeutic drug resistance." (PMID 31671668, 2019). "The use of chemotherapeutic drugs together with PFKFB3 inhibitors may improve response rates as well as progression-free survival in cancer patients." (PMID 30234009, 2018). "Targeting the glycolytic PFKFB3 enzyme is being studied as a therapeutic strategy against cancer." (PMID 30250201, 2018). "Indeed, siRNA suppression of PFKFB3 has been reported to reduce cancer cell viability while small molecule inhibitors of the PFKFB3 isoenzyme have been developed." (PMID 30234009, 2018). "Furthermore, circulating MDSCs were markedly reduced in advanced cancer patients treated with PFKFB3 inhibitor." (PMID 30123774, 2018). "However, the study of PFKFB3 has mainly focused on its role in the metabolic pathways of cancer cells." (PMID 29559632, 2018). "A large number of studies have reported that increased PFKFB3 expression promotes proliferation and carcinogenesis, indicating that its inhibition could be crucial for treating inflammation and cancer." (PMID 30234009, 2018). "PFKFB3 has also a key role in the interaction between cancer cells and other cells in the TME." (PMID 30234009, 2018). "Here, we reveal a role for PFKFB3 in HR repair of DNA DSBs in cancer cells." (PMID 30250201, 2018). "In the clinic, the radiation dose set to kill cancer cells in patients is limited with respect to normal tissue tolerance, thus our findings suggest PFKFB3 inhibition as an attractive approach to potentially achieve cancer-specific DNA repair deficiency upon radiation therapy." (PMID 30250201, 2018). "CO inhibition of CBS in various cancer cells has been shown to affect the methylation state of 6-phosphofructo-2-kinase/fructose-2,6-biphosphatase 3 (PFKFB3), suppressing 6-phosphofructo-2-kinase, resulting in a shift of glucose from glycolysis to the pentose phosphate pathway." (PMID 30050658, 2018). "Importantly, inhibition of PFKFB3 by small-molecule PFK15 effectively enhances cisplatin-induced apoptosis of cancer cells." (PMID 29410405, 2018). "The PFKFB3 isoform is favored in malignant cells with its enzymatic activity following its expression, thus its enzymatic activities represent an attractive anti-cancer drug target." (PMID 30250201, 2018). "As a resistance mechanism utilized by cancer cells to avoid being destroyed, autophagy stimulated by PFKFB3 inhibition may serve as a protective measure." (PMID 28977989, 2017).
cancer (continued). "Overall, whether the ‘less is more’ paradigm shift is also relevant in the human cancer setting requires further study, but these preclinical studies nonetheless raise concerns about the unconsidered use of ‘maximal tolerable doses' of PFKFB3 blockers." (PMID 29263247, 2017). "Some stoma cells in cancer tissues were also PFKFB3 positive." (PMID 28061878, 2017). "A clinical trial using a small chemical PFKFB3 blocker has been initiated to target, in the first instance, cancer cells by using maximally tolerated doses, based on preclinical studies designed to inhibit cancer cell proliferation." (PMID 28081641, 2017). "Consequently, further study is needed to elaborate the exact role of PFKFB3 in different cancer cells." (PMID 29263928, 2017). "Taken together, these data demonstrated that PFKFB3 inhibitors may be able to universally overcome resistance to targeted cancer therapies." (PMID 28977989, 2017). "Of course, it is critical to explore whether PFKFB3 inhibitors affect the metabolism of normal cells and cancer stem cells (CSCs)." (PMID 28977989, 2017). "For instance, recent data have indicated that glycolysis-targeting interventions such as the depletion of PFKFB3 may exert antineoplastic effects by limiting vessel sprouting, hence targeting both proliferative endothelial and cancer cells." (PMID 29109698, 2017). "These researchers revealed that inhibition of PFKFB3 could suppress glycolysis and induce G2 phase cell cycle arrest in cancer cells instead of iPS and fibroblasts." (PMID 28977989, 2017). "PFKFB3 suppression can induce the apoptosis of cancer cells and halt cell cycles." (PMID 28061878, 2017). "Even under the same stimuli, cancer cells also display diverse regulatory mechanisms for PFKFB3." (PMID 29263928, 2017). "The overexpression of PFKFB3 is fundamental to the targeted therapy of various cancer types." (PMID 28061878, 2017). "This study is the first to reveal the compartmentalisation of PFKFB3 in invading protrusions in cancer cells, as we found the co-localisation of PFKFB3 and the aggregation of F-actin (in both invadopodia and invadopodia) and ECM degradation spots (in invadopodia)." (PMID 28061878, 2017). "Because of this, inhibiting PFKFB3 has been considered an anti-cancer therapy." (PMID 27079271, 2016). "Of significance, CLOCK stimulated PFKFB3 expression through increasing the transcription activity of PFKFB3 promoter, which appeared to be responsible for distinct PFKFB3 rhythmic expression in cancer cells." (PMID 27079271, 2016). "As a pro-cancer gene, PFKFB3 has been shown to critically control cancer cell survivals." (PMID 27079271, 2016). "At the cellular level, the growth of most cancer cells displayed increased rates of glycolysis, where a regulatory step is controlled by PFKFB3, the gene that encodes for inducible 6-phosphofructo-2-kinase (iPFK2)." (PMID 27079271, 2016). "Clearly, circadian clocks critically control PFKFB3 expression, thereby cancer cell proliferation." (PMID 27079271, 2016). "PFKFB3 is known to regulate high glycolytic flux in cancer cells." (PMID 27669567, 2016). "Moreover, cancer and iPS cells, when cultured under hypoxic conditions, alter their expression level of PFKFB3 and PFK1 to resemble those in CSCs." (PMID 26337471, 2015). "Given that PTEN is frequently mutated or deleted in human cancer, it would be interesting to further investigate the correlation between loss of PTEN and a possible increase in PFKFB3 protein, which could then impact on glycolytic activity." (PMID 24280138, 2013). "These efforts have thus far mainly been concentrated on the inhibition of the PFK-2 activity of PFKFB3, as it is induced by several oncogenes as well as hypoxia and may contribute to the high glycolytic activity observed in cancer cells." (PMID 24280138, 2013). "The remaining 7 genes with exception of PFKFB3 are not linked to cancer when reviewing the literature." (PMID 24165198, 2013).
cancer (continued). "Despite the potential merits, exploitation of PFKFB3 for cancer therapy has remained poor." (PMID 21957443, 2011). "Taken together, these studies suggest PFKFB3 is a potential target for a new class of anti-neoplastic agents that prevent onset of the cancer-specific glycolysis by inhibiting the Fru-2,6-BP surge and, eventually, induce death of cancer cells." (PMID 21957443, 2011). "Accordingly, inhibition of PFKFB3 as a therapeutic strategy for cancer has been suggested." (PMID 21957443, 2011). "Thus, PFKFB3 has important functions in cancer cells, including glycolysis and proliferation." (PMID 40022029, 2025). "Moreover, PFKFB3 expression is upregulated by transcription factors such as the Ets transcription factor (PU.1) and STAT3, which are associated with chemoresistance in cancers." (PMID 40264038, 2025). "Interestingly, PFKFB3 expression can regulate glycolysis in tumor cells and cancer cells." (PMID 38510704, 2024). "PFKFB3 inhibition tightens the vascular barrier by reducing VE-cadherin endocytosis in ECs and reduces glycolysis to make cells more quiescent and adherent (by upregulating N-cadherin); it also reduces NF-κB signaling to reduce the expression of cancer cell adhesion molecules in ECs." (PMID 39729352, 2024). "A key role for PFKFB3 enzymatic activity in homologous recombination repair was confirmed, a selective PFKFB3 inhibitor that could potentially be used as a strategy for the treatment of cancer." (PMID 37253634, 2023). "We found a significant positive association between PFKFB3 expression level and neutrophil, macrophage, and myeloid dendritic cells infiltration in pan-cancer; and a negative correlation between PFKFB3 expression level and NK cells and B cells infiltration in pan-cancer." (PMID 37253634, 2023). "Interestingly, PIM2 can also phosphorylate the glycolysis regulator PFKFB3 (6-phosphofructo-2-kinase/fructose 2,6-bisphosphatase 3), overexpressed in many cancer cells, leading to activation of PFK1 (phosphofructokinase 1), the third enzyme of the glycolytic pathway." (PMID 37958880, 2023). "We also investigated their biological roles in OSCC cells, which PFKFB3 is linked to critical aspects such as cell survival, G2/M cell cycle progression, invasion, and migration, while PFKFB4 is strongly associated with drug resistance and the acquisition of cancer stemness characteristics." (PMID 37919747, 2023). "Thus, PFKFB3-targetting inhibitors are promising in cancer cells." (PMID 36077431, 2022). "In addition, PFKFB3 is commonly overexpressed in breast, colon, ovarian, and thyroid cancers but is expressed at low levels in normal tissues and is the basis of targeted therapy for a variety of cancers." (PMID 36230492, 2022). "Besides, PFKFB3 induced chemoresistance to protect cancer cells from apoptosis and blockage of PFKFB3 could effectively alleviate the malignant phenotype." (PMID 35094634, 2022). "Thus, the DNA-damage-induced PFKFB3 recruitment upon cancer transformation and platinum resistance could be to favor DNA repair as an adaptive mechanism." (PMID 34298817, 2021). "Finally, we discuss potential combination therapies using PFKFB3 inhibitors, which may represent important future cancer treatment options." (PMID 33671514, 2021). "Moreover, overexpression of PFKFB3-4 fusion protein blunted cell viability and anchorage-independent growth of U87 cells, and its expression level inversely correlated with the growth rate of several human cancer cell lines." (PMID 34234350, 2021). "Thus, PFKFB3 has critical roles in cancer cells by linking glycolysis to cell proliferation." (PMID 32198345, 2020). "Cancer-induced mutations and alterations of signaling pathways activate PI3K-Akt, which promotes transcriptional induction of glucose transporters [e.g., glucose transporter 1 (GLUT1)], activation of glycolytic enzymes (e.g., HK2, PFKFB3), and parallel activation of mTOR." (PMID 30123774, 2018).
cancer (continued). "Therefore, PFKFB3 may also control the protrusions in cancer cells, and inhibiting this gene presents a promising strategy for alleviating the aggressive behaviour of cancer cells." (PMID 28061878, 2017). "Therefore, we propose the efficacy of PFKFB3 inhibitors as anti-cancer agents may be improved in combination with autophagy inhibitors." (PMID 28977989, 2017). "Furthermore, we predict that PFKFB3 inhibitors in combination with targeted cancer agents may improve response rates as well as progression-free survival." (PMID 28977989, 2017). "When cultured under hypoxic conditions, iPS cells and cancer cells change the expression levels of PFKFB3 and PFK-1 similarly in CSCs, supposing that CSCs might enhance glycolysis due to hypoxia-mediated modulation of restriction point (R-point) markers such as PFK-1 and PFKFB3." (PMID 29263928, 2017). "However, future study is needed to elucidate the mechanisms underlying the effect of PFKFB3 inhibition on reducing CLOCK expression, and to determine the extent to which other CLOCK-associated mechanisms contribute to the anti-cancer effect of 3PO in a timed manner." (PMID 27079271, 2016). "Given this, how to effectively inhibit PFKFB3 could be key to a better anti-cancer treatment." (PMID 27079271, 2016). "Thus it is likely that glycolysis-promoting enzymes like PFKFB3 may be differentially regulated in iPS, CSCs and cancer cells." (PMID 26337471, 2015). "Moreover, PFKFB3 expression in cancer cells and CSCs is comparable." (PMID 26337471, 2015). "In dendritic cells, the use of PFKFB3 inhibitor PFK15 will inhibit the glycolysis and function of DCs, thus affecting the effect of cancer immunotherapy." (PMID 41000074, 2025). "Additionally, FBP fosters a feedback loop involving phosphofructokinase-1 (PFK1), PI3K/Akt, and PFK2/PFKFB3, thereby promoting aerobic glycolysis and sustaining the Warburg effect in cancer cells, and further investigation is needed to determine whether this effect exists during decidualization." (PMID 40034230, 2025). "We chose the A-498 (HTB-44) cancer cell line because of its high rate of glycolysis and its expression of both PFKFB2 and PFKFB3 isoforms (Ref." (PMID 40402947, 2025). "Our results demonstrate that PFKFB3 inhibition by 3PO increases radiation-induced cell death of CRC cells while reducing cancer cell migration and cancer cell invasion during RT in vitro." (PMID 39007350, 2024). "The targets for HIF-1α include LDH-A, PFKFB3, PDK-1, and PDK-3; therefore, the expression and activities of these proteins are increased in cancer cells." (PMID 38339256, 2024). "Two isoforms of this enzyme, namely PFKFB3 and PFKFB4, are upregulated in cancer cells, leading to increased levels of fructose-2,6-bisphosphate to rescue glycolysis from the negative feedback regulation by ATP." (PMID 38339256, 2024). "Currently, potent and selective inhibitors of PFKFB3, such as PFK-015 and PFK-158 have been identified and undergone clinical trials for treating late-stage patients with cancer." (PMID 38622715, 2024). "PFKFB3 is an inducible member of the PFKFB family and is upregulated in numerous cancers, likely contributing to dysregulation of glucose metabolism and contributing to aerobic glycolysis." (PMID 39763797, 2024). "Hence, our results indicate that PFKFB3 inhibition by 3PO could be a potential therapeutic target in human RC, reducing cancer cell survival in vitro and inducing TVN in vivo, which ultimately may improve the currently established therapy to increase the rate of clinical complete responses." (PMID 39007350, 2024). "We further explored the effects of PFKFB3 and PFKFB4 on chemoresistance and cancer stemness in OSCC cells." (PMID 37919747, 2023). "Two isozymes of PFK2, i.e. PFKFB3 and PFKFB4, showed elevated expression in many cancer types and are involved in altered glycolysis." (PMID 37222403, 2023).